FAM87B (family with sequence similarity 87 member B)
Synonyms: FLJ40008
Gene: Long non-coding RNA gene on chromosome 1 (817,363 to 819,842, forward strand). Ensembl gene ENSG00000177757.
Diseases named in the same sentence as FAM87B in open-access papers:
FAM87B is named in the same sentence as 3 diseases in open-access papers, as found by Europe PMC text mining. Sharing a sentence is not in itself a finding about the gene and the disease. The quoted sentences say what the papers report.
bladder cancer (1 paper, 2022). "The results showed that PCAT7 and UBE2Q1-AS1 LncRNA genes were lowly expressed in human bladder cancer tissues, while LINC01184 (SLC12A2-DT), MPP7-DT, FAM87B were expressed to a great extent in human bladder cancer tissues." (PMID 36454396, 2022). "Five commonly used CRLs were selected for experimental verification by qRT-PCR, including PCAT7, LINC01184 (SLC12A2-DT), MPP7-DT, FAM87B and UBE2Q1-AS1 in human bladder cancer tissues and normal bladder tissues (Normal bladder tissues are assigned to the low-risk group)." (PMID 36454396, 2022).
osteosarcoma (1 paper, 2021). A usually aggressive malignant bone-forming mesenchymal neoplasm, predominantly affecting adolescents and young adults. "Herein, we screened 6 osteosarcoma-related genes by lncRNA microarray, MALAT1, HCG9, FAM99A, FAM87B, DLEU2, and C8orf49." (PMID 34456631, 2021). "Six genes presented statistically significant expressions (P < 0.05) in osteosarcoma tissues versus paracarcinoma tissues and were screened, which were MALAT1, HCG9, FAM99A, FAM87B, DLEU2, and C8orf49." (PMID 34456631, 2021). "FAM99A, FAM87B, and C8orf49 have not been reported in osteosarcoma studies and are rarely reported in other cancers." (PMID 34456631, 2021).
FAM87B also shares sentences with these, for which no sentence is quoted: cancer (1 paper).